CD40 (CD40 molecule)
Diseases named in the same sentence as CD40 in open-access papers (continued):
Sharing a sentence is not in itself a finding about the gene and the disease.
tumor (continued). "In contrast, the combination of Y27632 and Dox increased CD40 and CD86 expression as well as cross-presentation of OVA-derived peptide to MHC-I in DCs from tumour-draining LNs of B16F10-Ova tumour-bearing mice." (PMID 29867097, 2018). "Conventional and monocyte-derived dendritic cells in the tumor-draining lymph nodes (dLN) of C57BL/6 and PLT2 mice were similarly increased after Poly I:C immunotherapy, and expressed high levels of CD40 and CD86." (PMID 30383838, 2018). "Specifically, IL-2/CD40 reduced expression of several regulatory molecules (CD39, A2AR, A2BR, PD-L1, ICOS, and/or IL-10) on young tumor-infiltrating CD11c+ cells and CD4+ T cells, suggesting reduced suppressive activity." (PMID 30560130, 2018). "Meanwhile, MHCII, CD40 and CD80 genes expression showed significant increasing in comparison to PBS; these findings suggested that DCs effectively recognized tumor antigens and efficiently presented to T cell." (PMID 29959375, 2018). "Antibody binding to CD40-activated APC cells and, in consequence, triggered tumor specific T-cell immune response." (PMID 28660349, 2018). "This is supported by studies from our laboratory showing that CD8+ T cells are important anti-tumor effector cells during IL-2/CD40 treatment, and other studies showing that DCs, CD8+ T cells and IFN-γ are required for IL-2/CD40-mediated tumor regression." (PMID 30560130, 2018). "One advantage sustained release of CD40 mAb from SRB which enables the persistent and the contemporaneous presence of antigen and adjuvant signaling in the tumor microenvironment, during RT." (PMID 29594038, 2018). "There was also a significantly reduced % of circulating mDC1shigh and pDCshigh and reduced expression of HLA-DR, CD40, and CD83 on mDC1shigh and HLA-DR on pDCshigh in those patients whose tumours showed a PPR to NAC." (PMID 28913366, 2017). "Treatment with laminarin induced significant increases in the CD40, 80, and 86 and MHC classes I and II expression levels in tumor drLNs and spleen DCs." (PMID 28423736, 2017). "The activating molecules, CD40 and TLR8 ligand, seemed to enhance T cell proliferation for both CD8+ and CD4+ T cells co-cultured with tumor cells, fibroblasts and spheroid polarized MDMs stronger than the inhibiting molecules." (PMID 28750018, 2017). "We have previously observed that CD40 is strongly upregulated in the transgenic inflamed skin and it is also expressed in NPC tumour samples." (PMID 29228057, 2017). "In this regard, agonist CD40 antibody and the cognate CD40 ligand (CD40L) are candidates for tumor immunotherapy." (PMID 29129918, 2017). "In our model, DC maturation with up-regulation of CD40, CD80 and CD86 was measured in tumor draining LN after IL PV-10." (PMID 27177220, 2016). "All CD40+, CD80+, CD86+ and MHC-II+ of DCs were significantly up-regulated upon the cGAMP treatment in tumor-bearing mice." (PMID 26754564, 2016). "The promotion of tumour growth by CD4+ helper T cells and CD8+ T cells is subdued with the intervention of CD40-mediated inflammatory E-cadherin + DCs." (PMID 25651850, 2015). "Activation of T cells requires 3 signals: recognition of tumor cell antigen, activation of costimulatory molecules (CD80/CD28 and CD40/CD40L), and binding of cytokines (IL-1, IL-2, IL-6, IL-12, and IFN-γ)." (PMID 26605342, 2015). "In tumor bearing Tgfbr1/Pten 2cKO mice, PD-1 blockade increased MHC-II+, CD40+, CD86+ cells in spleen." (PMID 26573233, 2015). "To investigate the role of CD40 in CXCR5 expression regulation, we compared CXCR5 expression in bone marrow and tumor tissues from the MDSC of WT and KO mice." (PMID 26462153, 2015). "Co-expression of CD40 and CD40L contributes to oncogenic process of malignancy in vitro, increasing tumor proliferation, motility and invasion by activation CD40L/CD40/NF-jB pathway." (PMID 26313265, 2015).
tumor (continued). "Resembling the results obtained with tumor-induced splenic MDSCs, BM-MDSCs incubated with VSSP showed a higher expression of CD11c, CD11b, Gr1 and CD40 than untreated control cells." (PMID 24829762, 2014). "The role of the CD40/CD40L pathway in the induction of body immunity, in inflammation, or in hemostasis has been well documented, whereas its involvement in neoplastic disease is still under investigation." (PMID 25117071, 2014). "The combination therapy of partial debulking surgery, IMQ and anti-CD40 significantly delayed tumor growth in a CD8 T cell dependent manner, and promoted tumor regression in 25% of animals with establishment of immunological memory." (PMID 25518732, 2014). "Previous studies have reported the expression of CD40 on MDSCs to be important in MDSC-mediated immune suppression and Treg expansion in certain tumor models." (PMID 25009656, 2014). "The role of the CD40/CD40L pathway in the induction of body immunity, in inflammation, or in hemostasis has been well documented, whereas its involvement in neoplastic disease is still controversial." (PMID 25117071, 2014). "Checkpoint inhibitors (anti-CTLA4, anti-PD-1/anti-PD-L1, anti-LAG-3, anti-BTLA), as well as agonists of CD40 or TLR, are also known to improve anti-tumor T cell survival." (PMID 25325015, 2014). "Tumor-bearing mice were given intra-tumoral injections of PBS (control), soluble anti-CD40 alone, soluble CpG + anti-CD40 and anti-CD40/CpG liposomes." (PMID 25380524, 2014). "Immunosuppressive DC isolated from late-stage tumor-bearing animals downregulated MHC class II and CD40 expression but significantly upregulated the co-inhibitory molecule B7-H1 and exhibited arginase I activity comparable to that seen in MDSC." (PMID 23874338, 2013). "Forty-eight hours later, mice were euthanized and the maturation status of DC within the spleen and tumor-draining lymph nodes (TDLN) was assessed using flow cytometry by costaining for CD11c and the maturation markers CD80, CD86, I-A/I-E, and CD40." (PMID 23935927, 2013). "Our study shows that TRF increased the expression of CD40 and CD80 in the DC-pulsed with tumor lysate in a dose-dependent manner." (PMID 24069344, 2013). "Based on published evidence indicating a therapeutic potentials in several tumor models we tested mAbs to CD137, CD40, CTLA-4, PD-1, TIM-3 and LAG-3, as single agents and in combinations." (PMID 24367702, 2013). "In the presence of anti-CD40, CTLs are primed in vivo and prevent OVA+ expressing tumor cell growth." (PMID 24228179, 2013). "There was an enhanced expression of CD40 and CD80 in the tumor lysate (TL)-pulsed DC that was co-cultured with TRF as compared to DC alone." (PMID 24069344, 2013). "Most importantly, combination of MRF/magnetic field and anti-CD40/IL2 resulted in significantly greater inhibition of both primary and contralateral-tumor growth." (PMID 23133545, 2012). "DCs were evaluated for antigen uptake, and following maturation with LPS and IFN-gamma, DCs were assessed for expression of CD80, CD40, CD86, ICAM-1 and CCR7, production of IL-12p70 and IP-10, and induction of tumor-specific T-cell responses." (PMID 22194898, 2011). "The results presented in this paper, together with our previous work, suggest that co-expression of CD40 and CD40L and resultant constitutive activation of the CD40 signal pathway are of primary importance in understanding the process of tumor invasion." (PMID 19865524, 2009). "Agonist CD40 antibodies have been previously shown in murine models to activate APC and enhance tumor immunity; in humans, CD40-activated DC and B cells induce tumor-specific T cells in vitro." (PMID 19906293, 2009). "One possibility suggested by the strict requirement for NK cells is that NK cells interact with tumor cells treated with TSA (and expressing CD40) as described for DC and enhance antigen presentation." (PMID 18070359, 2007). "Therefore, CD40 signaling may either protect or enhance the apoptotic signal in tumor cells." (PMID 16545138, 2006).
tumor (continued). "A similar situation is observed in neoplastic CD40 expressing B lymphoma cells, where CD40L has been reported to promote either cell survival or tumor regression." (PMID 16545138, 2006). "In models in which DCs are generated in vitro, CD40 stimulation can induce increased DC survival and IL-12 secretion, thus promoting IFN-γ production by T-helper cells as well as tumor-specific cytotoxic responses." (PMID 16417648, 2006). "In this perspective, we have investigated the expression of the CD40, CD80, CD86, PD-1L, B7H2, OX40L and 4-1BBL costimulatory molecules in 10 human NB cell lines, as well as in primary tumour cells isolated from NB patients." (PMID 12771917, 2003). "IFNγ receptor (Ifngr1) expression was required on host cells, not tumor cells, for CD40 agonist-mediated tumor control." (PMID 41676732, 2026). "Tumors were treated by intratumoral administration of MBTA, a formulation containing resiquimod, poly(I:C), LTA, anti-CD40 antibody, and mannan-BAM (a phagocytosis-stimulating mannan anchored to the tumor cell membrane via a biocompatible membrane anchor, BAM)." (PMID 42318705, 2026). "CD40, a member of the tumor necrosis factor superfamily, induces growth arrest and apoptosis when overexpressed in tumor cells and activates dendritic cells to enhance CD4+ and CD8+ T cell anti-tumor effects." (PMID 41514678, 2026). "Additionally, it has been noted the use of vaccines based on irradiated tumour cells combined with immune-stimulating agents like mannan-BAM, TLR agonists and anti-CD40 antibody to induce an immune response against the tumour mass." (PMID 41601679, 2026). "employed 10X Visium on two MC38 colon adenocarcinoma mouse samples treated with anti‐CD40 antibodies, revealing clusters of NRF2‐activated, tumour‐promoting TAMs in peri‐necrotic haemorrhagic tumour regions, resembling anti‐inflammatory erythrophagocytic macrophages." (PMID 40677104, 2025). "This reveals that the presence of CD40 on host antigen-presenting cells and/or tumor stromal cells is not essential for the successful rejection of the TAg+ cancer cells." (PMID 40397730, 2025). "Furthermore, CD40‒HER2 BsAb‐11 delayed tumour growth in both MC38‒hHER2 and MB49‒hHER2 hCD40tg mouse models compared to CD40 mAb‐H‐N297A." (PMID 40726342, 2025). "Given the well-established role of CD40 in antitumor immunity, this correlation suggests that PRSS2 may participate in the regulation of the tumor immune microenvironment." (PMID 41141930, 2025). "Its correlations with key immune-related genes, including TRBV, CD40, and TSC22D1, suggest that PRSS2 may be involved in tumor immune regulation, potentially contributing to improved clinical outcomes." (PMID 41141930, 2025). "Looking at the DC phenotypes in more detail, pDC and cDC1 in tumor tissues and to a lesser extent in liquid samples demonstrated a more mature phenotype based on significantly higher proportions positive for CD86 and CD40." (PMID 41221283, 2025). "However, CD40, glypican 3 (GPC3), Iroquois homeobox 2 (IRX2), FOXO1, EPAS1, and cyclin-dependent kinase inhibitor 1C (CDKN1C) were consistently down-regulated in tumor tissues and GbPDTOs compared to those in normal tissues." (PMID 41376821, 2025). "Tumor biopsies confirmed successful co-localization of MP0317 with FAP and CD40." (PMID 40700292, 2025). "In a landmark mouse model study, CD40 agonist therapy alone induced substantial tumor shrinkage without requiring PD-1 or CTLA-4 checkpoint inhibition, highlighting a potent innate immune mechanism." (PMID 40821795, 2025). "In contrast, CD40 mAb‐H‐mIgG1 treatment showed no significant tumour growth difference upon macrophage depletion, highlighting distinct mechanisms between BsAb‐11 and CD40 agonist." (PMID 40726342, 2025). "The CD40 costimulatory molecule is a member of the tumor necrosis factor (TNF) receptor superfamily, and is expressed on various antigen-presenting cells (APCs), as well as some tumor cells." (PMID 40864758, 2025).
tumor (continued). "This analysis confirmed that while key immune checkpoint transcripts were enriched in the high-CD40 group, non-immune-related genes (tumor markers, antigens, and proliferation) were not." (PMID 41182434, 2025). "TME cells potentially support tumor cell survival through CD40- and BAFF-mediated signaling, while tumor cells may induce T cell and NK exhaustion via TIM3 coinhibitory signaling." (PMID 40876452, 2025). "The administration of Delta-24-RGD and anti-CD40 was able to initially control tumor growth in Batf3ko mice lacking cross-presenting DCs (type 1 conventional dendritic cell [cDC1]), similar to the wild-type mice." (PMID 40578365, 2025). "Additionally, a subpopulation expressing FcγRI/CD64 with elevated CD40 and CCR7 levels—indicative of their role in T cell-mediated tumor immunity—is diminished." (PMID 40058234, 2025). "Similarly, biologicals such as CD40 agonist antibodies or small molecules such as TLR agonist enhanced MHC-IIhi proinflammatory TAMs differentiation and enhanced CD8+ T cell anti-tumor activity 45-47." (PMID 39816692, 2025). "By binding to CD40 on macrophages, CP-870,893 activates NF-κB and MAPK pathways, enhancing antigen presentation, promoting pro-inflammatory responses, and driving M1 polarization to strengthen anti-tumor immunity." (PMID 39575419, 2024). "An animal demonstrated that combination therapy with a CD40 agonist resulted in a superior effector response compared to anti-PD-1 monotherapy for CCA, accompanied by an increased presence of CD4+ T and CD8+ T cells in tumor-bearing mice." (PMID 39845973, 2024). "It showed non-MDSC tumor-resident myeloid populations produced CCL5 in response to CD40 activation, but not in response to immune checkpoint blockade, and CCL5-recruitment of CD4+ T cells mediated treatment efficacy." (PMID 38786066, 2024). "The interaction between CD40 and CD40L can promote cell proliferation, supporting tumor growth." (PMID 39625893, 2024). "Conversely, CD24, CD31, and CD40, though not overexpressed in tumor samples, showed a significant correlation with nodal involvement in LCa patients (p < 0.01)." (PMID 38902710, 2024). "However, when TGF-β signaling is inhibited, the suppressed expression of MHC II, CD40, CD80, and CD86 on DCs by tumor supernatant is substantially attenuated." (PMID 38164187, 2024). "Other groups that received either a free injection of anti-CD40 or one fraction of 6 Gy alone also showed some tumor growth inhibition but not as much as with LIFE Biomaterial treatment groups." (PMID 38539546, 2024). "Treatment with 2141-V11 led to rejection of both injected and non-injected tumors, suggesting that the CD40-targeting Ab led to a systemic and robust immune activation, extending beyond the local tumor." (PMID 38883779, 2024). "Recently, Selicrelumab (an agonistic CD40 monoclonal antibody) is being evaluated as a neoadjuvant therapy that induces T-cell activity and proliferation in the TIME, more mature DCs, decreases the number of M2 TAMs, and reduces tumor fibrosis." (PMID 38167055, 2024). "Therefore, compared to anti-CD40+Flt3L, TNFR1 blockade was more effective in increasing the number of intratumor immunostimulatory DCs, which was reflected in better control of tumor growth." (PMID 39178856, 2024). "The levels of sCD40 have been distributed based on tumor stage (T1+T2, T3+T4) or lymph node involvement (No, N1+N2+N3) with regard to CD40 (RS1883832)." (PMID 39625893, 2024). "Several groups reported that CD40 agonist antibodies and recombinant soluble CD40L could activate anti-tumor immune responses both in pre-clinical studies." (PMID 39306655, 2024). "IFNs stimulate DC expression of the costimulatory molecules CD40, CD80, CD86, and mayor histocompatibility complex (MHC) class-II, promoting their maturation, the ability to present tumor antigens and migratory capabilities." (PMID 39682686, 2024).
tumor (continued). "In prior work, we also noted that this toxicity was improved by lowering (by 50%) the dose of the IT-IC or the anti-CD40, without a detectible decrease in anti-tumor efficacy." (PMID 38731089, 2024). "We treated 4662 tumor-bearing mice with a single dose of gemcitabine (G) and/or nab-paclitaxel (A), seven doses anti-PD-1 Ab (P) and/or three doses of anti-CTLA-4 Ab (C) every three days, and one dose of agonistic anti-CD40 Ab (F)." (PMID 38378697, 2024). "Significant delay in tumor growth was observed for the group that received CLARITY biomaterial_Mn2O3 loaded with 100 μg of anti-CD40 (*, p = 0.0212) compared to the no-treatment group." (PMID 39452584, 2024). "Inhibiting CD40 signaling could disrupt the survival signals that HRS cells rely on, potentially leading to increased apoptosis and reduced tumor growth." (PMID 39682256, 2024). "Engagement of CD40 can be achieved not only through its cognate ligand but also through agonistic Abs, which promote APC maturation and activation, resulting in T-cell responses and elimination of tumor cells." (PMID 38883779, 2024). "Furthermore, in multiple anti-PDL-1 resistant murine tumors with poor T-cell infiltrate, a combination of FLT3L, radiation, polyIC, and CD40 agonist was able to reverse anti-PDL-1 resistance, induce tumor regression, and establish antitumor memory." (PMID 38903502, 2024). "Studies have shown that CD40 activation prompts macrophages, but not T cells, to rapidly infiltrate tumors, become tumor-killing and promote tumor mesenchymal depletion." (PMID 38495490, 2024). "Moreover, a study demonstrates that using a nanofluidic drug-eluting seed (NDES) for sustained, low-dose intratumoral delivery of CD40 monoclonal antibody can alter the TME and reduce tumor size in mouse models of PDAC." (PMID 38835055, 2024). "CD40 is expressed on B-cell lymphoid tumors and a proportion of solid tumors but the level of CD40 expression on tumor cells did not correlate with clinical responses." (PMID 38153346, 2024). "Additionally, combining CD40 agonists with anti-PD-1 and anti-CTLA4 monoclonal antibodies has shown synergistic effects, enhancing anti-tumor responses." (PMID 39120299, 2024). "In addition, the expression of receptors, including TNFSF14, CD40, LTBR, and VTCN1, was elevated in LN-out tumor cells." (PMID 38519500, 2024). "CD40 activation can significantly affect the tumor microenvironment, independent of innate immune sensors." (PMID 39188680, 2024). "The tumor-infiltrating cDC1 and cDC2 displayed a migratory and activated phenotype shown by CD40 and CCR7 expression, the RNA-seq data revealed overall upregulation of Cd40, Cd86 but also the cytokine Il12 in BRAFi-sensitive tumors." (PMID 38631706, 2024). "The tumor on one flank was then treated using LIFE Biomaterial prepared with the immunoadjuvant anti-CD40, with/without radiotherapy at 6 Gy." (PMID 38539546, 2024). "Our findings indicated a significantly (p < 0.05) higher expression of protein biomarkers associated with the presence and activity of immune cells, including CD45, CD3, CD68, CD163, CD11c, CD8, HLA-DR, CD40, PD-L1, and IDO1, in the tumor compartments of patients with CR compared to those with PD." (PMID 39049036, 2024). "However, combination regimens that included agonistic anti-CD40 Ab and ICB resulted in tumor regressions and prolonged survival, including complete responses (CRs)." (PMID 38378697, 2024). "Taken together, our results suggested that upregulation of CD40, CTLA4, ARG1, STAT3, IDO, and CD274, which were included in tumor inflammation signature, in the TME of KRASmut, could be characteristic of immune suppression." (PMID 36831441, 2023). "Authors also found that the single treatment with CD40 ab therapy in mice decreased the PD-1 expression on tumor cells and also changed the T cell phenotype, which helped increase the expressions of IFN-gamma, Ki-67, and granzyme-B, helping clear the tumor." (PMID 36769180, 2023).